XPC (XPC complex subunit, DNA damage recognition and repair factor)
Diseases named in the same sentence as XPC in open-access papers (continued):
Sharing a sentence is not in itself a finding about the gene and the disease.
colon cancer (4 papers, 2016 to 2023). "Taken together, BAX and BAK deficiency in the DLD-1 colon cancer cells downregulated the expression of XPC and altered the energy metabolism of cancer cells via the upregulation of glycolysis implicating the development of drug resistance." (PMID 31551763, 2019). "To validate this result, we abrogated XPC function by CRISPR/Cas9 in nine other colon cancer cell lines, namely HT-29, HCT-15, RKO, COLO205, LoVo, HCT116, Caco2, SW480 and SW620." (PMID 38058548, 2023). "Strikingly, the only exception was GG-NER, as impairment of XPC or DDB2 had no impact on the sensitivity of DLD-1 colon cancer cells to oxaliplatin, while it did cause hypersensitivity to cisplatin." (PMID 38058548, 2023). "We treated the panel of colon cancer cells and their isogenic XPC knock-out (KO) counterparts with oxaliplatin and observed that in 6 out of 10 cell lines XPC loss did not lead to increased sensitivity to oxaliplatin." (PMID 38058548, 2023). "One study investigating a possible relationship between DNA damage repair and drug response revealed that siRNA mediated downregulation of the damage recognition NER protein XPC increased cisplatin sensitivity in colon cancer cells, while overexpression of XPC led to an increase in resistance." (PMID 33922989, 2021). "Therefore, we reported here a new molecular pathway of BAX/BAK-induced drug resistance of DLD-1 colon cancer cells which is mediated by the downregulated expression of the XPC gene via the further heightening of glycolytic process." (PMID 31551763, 2019). "In term of tumor sites, XPC rs2228001 A > C did not seem to confer predisposition to either colon cancer or rectal cancer." (PMID 27669310, 2016). "The altered expression of XPC may affect the sensitivity of DLD-1 colon cancer cells to etoposide by manipulating the glycolytic process, since cancer cells have the preference for acquiring cellular energy from aerobic glycolysis over the usual oxidative phosphorylation pathway." (PMID 31551763, 2019). "To further investigate the absence of oxaliplatin-DNA lesion recognition by XPC in a subset of colon cancer cell lines, we focused on the GG-NER pathway." (PMID 38058548, 2023). "Out of 2000 analyzed genes, DDB2, but not XPC nor HMGA2, significantly associated with hazard ratio of 2.1 in a group of oxaliplatin-treated colon cancer patients." (PMID 38058548, 2023). "The response of XPC knockdown was comparable to those observed in DLD-1 BAX–BAK DKO cells (IC50 value > 40 μmol; RF = 13.22) suggesting the enhancing role of XPC in the development of resistance in DLD-1 colon cancer cells model against chemotherapy." (PMID 31551763, 2019). "Taken together, we showed that oxaliplatin-DNA crosslinks are not recognized by XPC and therefore not repaired by GG-NER in a subpopulation of colon cancer cells." (PMID 38058548, 2023).
esophageal cancer (4 papers, 2018 to 2022). A primary or metastatic malignant neoplasm involving the esophagus. "Recently, XPC polymorphisms have been demonstrated to be associated with an increased risk for several types of human malignancies, such as lung, bladder, breast, and esophageal cancers." (PMID 31572446, 2019). "In esophageal cancer XPC may play a role as a risk factor for developing malignancy." (PMID 35530314, 2022). "Another polymorphism, XPC PAT +/+, was associated with decreased risk for esophageal cancer." (PMID 35530314, 2022). "For example, most of the genes on the trunk of sample ESCC12 (CCND1, EGFR, APC, TGFBR2, XPC, XPA, FLI1, and NUMA1) have been identified and initially reported on the esophageal cancer." (PMID 30540749, 2018).
gastric cancer (4 papers, 2014 to 2025). A primary or metastatic malignant neoplasm involving the stomach. "Another Chinese study demonstrated that patients with the CC genotype of XPC rs2228000 have a borderline significant decreased risk of developing gastric cancer compared with those with the CT+TT genotype." (PMID 30609649, 2019). "After the FPRP estimation, the genetic association between XPC rs2228000 and the risk of bladder, breast, and gastric cancers risk remain significant at the prior probability level of 0.1." (PMID 31710080, 2019). "Li and colleagues observed that the XPC rs2228000 TT genotypes were associated with shorter OS than the CC+CT genotype individuals in a study of Japanese gastric cancer patients." (PMID 30609649, 2019). "Several original studies have reported the role of XPC polymorphisms in gastric cancer risk, but the results are inconclusive." (PMID 24886180, 2014). "All studies published up to January 2014 on the association between XPC polymorphisms and gastric cancer risk were identified by searching electronic databases PubMed, EMBASE, Cochrane library, and Chinese Biomedical Literature database (CBM)." (PMID 24886180, 2014). "The association between XPC polymorphisms and gastric cancer risk was assessed by odds ratios (ORs) together with their 95% confidence intervals (CIs)." (PMID 24886180, 2014). "Moreover, we provided assessment evidence regarding the potential impact of XPC rs2228000 on the reduced susceptibility to gastric cancer in the Chinese population." (PMID 31710080, 2019). "Mutations of the XPC genes may increase gastric cancer susceptibility by causing a severe depression of NER and consequently altering DNA repair activity." (PMID 24886180, 2014). "Hence, we performed this meta-analysis including all published studies to investigate the association between the XPC polymorphisms and gastric cancer risk." (PMID 24886180, 2014). "This could cover the true associations of XPC gene polymorphisms with gastric cancer." (PMID 24886180, 2014). "To date, the XPC gene polymorphisms (Lys939Gln, Val499Arg, and PAT−/+) to gastric cancer risk have been a research focus in scientific community and have drawn increasing attention." (PMID 24886180, 2014). "Several potential concerns should be discussed for the non-significant associations between XPC polymorphisms and gastric cancer susceptibility." (PMID 24886180, 2014). "Therefore, the negative results of the association between XPC polymorphisms and gastric cancer risk should be interpreted with caution." (PMID 24886180, 2014). "Thus, no regard of these factors may confer the non-significance for the independent role of XPC polymorphisms in gastric cancer development." (PMID 24886180, 2014). "In contrast, CDH2 was downregulated in gastric cancer, while EPB41L3, DNASE2, and XPC showed no significant expression differences between gastric cancer and normal tissues." (PMID 40393971, 2025). "This meta-analysis based on current evidences suggested that the XPC polymorphisms (Lys939Gln, Val499Arg, and PAT−/+) did not contribute to gastric cancer risk." (PMID 24886180, 2014). "In conclusion, the result of this meta-analysis based on current evidences suggests that the XPC polymorphisms (Lys939Gln, Val499Arg, and PAT−/+) may not contribute to gastric cancer risk." (PMID 24886180, 2014).
hepatocellular carcinoma (4 papers, 2016 to 2022). A malignant tumor that arises from hepatocytes. "We found the expression of XPC gene was decreased in cancer tissues when compared with non-cancer tissues, which suggest that XPC protein functioned as protective protein in hepatocellular cancer." (PMID 26967386, 2016). "Human XPC was found to be overexpressed in hepatocellular carcinoma cells, and may contribute to chemotherapeutic resistance in these cells." (PMID 29283431, 2017). "Finally, some evidence supports a role of XPC in liver (hepatocellular) carcinoma development." (PMID 35530314, 2022).
acute myeloid leukemia (3 papers, 2014 to 2021). Acute myeloid leukemia (AML) is a group of neoplasms arising from precursor cells committed to the myeloid cell-line differentiation. "It remains unclear whether a mutation in the XPC DNA repair gene in this patient led to the development of acute myeloblastic leukemia or a change of tolerance to chemotherapy." (PMID 34446105, 2021).
cutaneous melanoma (3 papers, 2007 to 2025). A primary melanoma arising from atypical melanocytes in the skin. "Several reports have shown that polymorphisms in the XPC gene increase the risk of different tumor types, including smoking-related cancers and cutaneous melanoma." (PMID 17705814, 2007).
Fanconi anemia (3 papers, 2014 to 2023). Fanconi anemia (FA) is a hereditary DNA repair disorder characterized by progressive pancytopenia with bone marrow failure, variable congenital malformations and predisposition to develop hematological or solid tumors. "Tumors showed overrepresentation and overexpression of genes of all the DNA repair pathways, including the NER, BER, HR, MMR, and NHEJ, as well as the Fanconi anemia, all known to play a role in platinum resistance, while in normal lung only one DNA repair gene was overexpressed, the XPC in NER." (PMID 25325012, 2014). "In addition to XPC, the other NER factors such as CSA and CSB, HR, and Fanconi anemia pathway-related factors are also involved in monoadducts and ICLs repair after the TMP/UV mutagenesis." (PMID 33828169, 2021).
neutropenia (3 papers, 2016 to 2024). A decrease in the number of neutrophils found in the blood. "Regarding neutropenia, we found two SNPs with the highest risk: C8orf34 rs1517114 GC (OR 1.50) and XPC rs2228001 GT (OR 4.63)." (PMID 36900216, 2023). "Regarding XPC, we found decreased overall survival in patients rs2228001 GT (HR 1.68) (also in TT to a lesser extent) and also a remarkably high odds ratio for neutropenia probability (OR 4.63)." (PMID 36900216, 2023).
pancreatic cancer (3 papers, 2019 to 2022). "Some XPC polymorphisms have been described as increasing pancreatic cancer risk, particularly in smokers with the rs2470353 and rs2607775 variants." (PMID 35530314, 2022). "However, one study suggested a protective role of the XPC-PAT polymorphism (PAT +/+) in pancreatic cancer risk." (PMID 35530314, 2022). "XPC may play a role as a risk factor for developing pancreatic cancer." (PMID 35530314, 2022). "None-the-less, the specific role of NER, and specifically of XPC expression and epigenetic regulation, still need to be further explored in pancreatic cancer development." (PMID 35530314, 2022). "Other studies suggested a role for genetic variants of other NER associated proteins, including ERCC1, but not necessarily XPC as a risk factor for developing pancreatic cancer." (PMID 35530314, 2022).
adenoma (2 papers, 2007 to 2012). A neoplasm arising from the epithelium. "A recent animal study had shown that 100% of XPC-deficient mice develop spontaneous lung tumors, the majority of which were adenomas; furthermore, when the mice had XPC and Gadd45a deleted at the same time, their lung adenomas were progressing to non-small cell lung adenocarcinomas." (PMID 17498315, 2007).
cataract (2 papers, 2016 to 2017). Partial or complete opacity of the crystalline lens of one or both eyes that decreases visual acuity and eventually results in blindness.
cutaneous squamous cell carcinoma (2 papers, 2018 to 2020). "While plausible as a mechanism for ETS-related mutation hotspots, we recently showed that TTCCG elements were associated with elevated mutation rates also in cutaneous squamous cell carcinomas (cSCCs) lacking global NER (XPC -/-)." (PMID 30586386, 2018).
emphysema (2 papers, 2025). "We previously observed both accelerated emphysema and NSCLC development in XPC-deficient (XPC KO) mice exposed to cigarette smoke (CS) and CS-carcinogens compared to those with wild-type XPC expression (XPC WT)." (PMID 40391767, 2025). "We found that XPC protected against CS-induced apoptotic cell death in non-cancerous bronchial epithelial cells (Beas-2B) and in chronic CS-exposed mouse lung with emphysema-like changes." (PMID 40391767, 2025).
lung disease (2 papers, 2025). "Chronic (6 months) cigarette smoke exposure through a smoking chamber decreases Xpc gene expression in mice and XPC deficiency increases emphysema-like lung disease in mice with age, exacerbated by cigarette smoke exposure." (PMID 40391767, 2025). "Chronic (6 months) cigarette smoke exposure through a smoking chamber decreases Xpc gene expression in mice and XPC deficiency increases emphysema-like lung disease in mice with age, exacerbated by cigarette smoke exposure 5,6,12." (PMID 40060594, 2025).
nasopharyngeal carcinoma (2 papers, 2024 to 2025). A carcinoma arising from the nasopharyngeal epithelium. "Different variation within XPC were reported to play a role in the development of nasopharyngeal carcinoma." (PMID 38686623, 2024).
neuroblastoma (2 papers, 2016 to 2021). Neuroblastoma (NB) is the most common solid, extracranial childhood tumor. "We investigated the associations between three XPC gene polymorphisms (rs2228001 A>C, rs2228000 C>T, and rs2229090 G>C) and neuroblastoma risk with 256 neuroblastoma patients and 531 healthy controls in a Chinese Han population." (PMID 27847809, 2016). "In view of this, we investigated the relationship between XPC gene polymorphisms (rs2228001 A>C, rs2228000 C>T, and rs2229090 G>C) and neuroblastoma susceptibility in a Chinese Han population making use of a total of 787 participants (256 cases and 531 controls)." (PMID 27847809, 2016). "In this hospital-based study comprising 256 cases and 531 controls, none of the three XPC gene polymorphisms was associated with neuroblastoma risk when compared to the reference genotypes." (PMID 27847809, 2016). "However, the associations between XPC gene polymorphisms and neuroblastoma risk have not yet been studied." (PMID 27847809, 2016). "However, there is no previous study investigating the association between XPC gene polymorphisms and neuroblastoma susceptibility." (PMID 27847809, 2016). "However, the association between XPC gene polymorphisms and neuroblastoma risk has not been studied." (PMID 27847809, 2016). "In summary, all the three XPC gene polymorphisms (rs2228001 A>C, rs2228000 C>T, and rs2229090 G>C) may not associate with neuroblastoma risk in the Chinese Han population." (PMID 27847809, 2016).
rectal cancer (2 papers, 2016 to 2018). A primary or metastatic malignant neoplasm that affects the rectum. "As for rectal cancer, subjects with high XPC expression demonstrated significantly decreased hazards of death in univariate model (HR = 0.40, 95% CI = 0.18–0.89, P = 0.026)." (PMID 29568775, 2018). "In this study, subjects with high XPC expression level suffer significantly decreased hazards of death for rectal cancer." (PMID 29568775, 2018). "High XPC expression demonstrated decreased death hazards in rectal cancer (HR = 0.40, P = 0.026)." (PMID 29568775, 2018).
squamous cell carcinoma of the skin (2 papers, 2022 to 2024). "Moreover, XPC knockdown in keratinocytes was associated with elevated levels of reactive oxygen species through altered AKT1 and NOX1 pathways, resulting in squamous cell carcinomas of the skin." (PMID 38672576, 2024).
African trypanosomiasis (1 paper, 2014). "Regarding the 16 up-regulated genes, S100A3, AXL, IL12A, XPC and FAS identified GO terms such as positive regulation of natural killer cell activation, response to UV-B, African trypanosomiasis, allograft rejection and Type I diabetes mellitus." (PMID 24756038, 2014).
cholangiocarcinoma (1 paper, 2025). A carcinoma that arises from the intrahepatic biliary tree (intrahepatic cholangiocarcinoma) or from the junction, or adjacent to the junction, of the right and left hepatic ducts (hilar cholangiocarcinoma). "In this context, our study extends these insights by demonstrating that the XPC rs2228001 variant confers significant prognostic implications in cholangiocarcinoma, highlighting the pivotal role of DNA repair capacity in shaping tumour progression and patient survival across diverse cancer types." (PMID 40833230, 2025).
chronic myelogenous leukaemia (1 paper, 2023).
colorectal adenoma (1 paper, 2022). An adenoma that arises from the colon or rectum. "The XPC polymorphism Ala499Val was found to play a protective role in developing advanced colorectal adenomas in smokers, and others have suggested a protective role of higher XPC mRNA and protein expression levels on colorectal survival, possibly related to an improved response to chemoradiation." (PMID 35530314, 2022).
dermatitis (1 paper, 2019). An inflammatory process affecting the skin. "In this prospective cohort study, we found that symptoms of dermatitis radiation, pain, pruritus and fatigue were associated with the expression level of some genes of the DNA-damage response pathway (FDXR, SESN1, XPC, ZMAT3, ATM, BCL2/BAX, and CDKN1A)." (PMID 31632918, 2019). "While the expression level of FDXR gene increased in patients experiencing a high grade of dermatitis radiation, those of SESN1, ATM, XPC, ZMAT3, CDKN1A genes decreased when radiation toxicity was manifested." (PMID 31632918, 2019).
diabetes (1 paper, 2016).
dysplasia (1 paper, 2024). A usually neoplastic transformation of the cell, associated with altered architectural tissue patterns. "Using a time course, we show that mice deficient in XPC develop earlier progression of pre-cancerous histologic changes from dysplasia to LUSC." (PMID 38672576, 2024). "We found tracheal dysplasia in both XPC WT and KO mice, which was observed as early as 8 weeks after NTCU treatment." (PMID 38672576, 2024). "Mice deficient in XPC are more likely to develop LUSC and progress to high-grade dysplasia earlier than mice expressing XPC." (PMID 38672576, 2024).
epithelioid cell melanoma (1 paper, 2021). A melanoma characterized by the presence of malignant large epithelioid melanocytes. "The results had shown a quite significant elevation in the stimulation of epithelioid cell melanomas in XPC (-/-) and INK4a/ARF (-/-) mice when being compared with XPC (-/-) and INK4a/ARF (+/+) mice." (PMID 34630850, 2021).
esophageal squamous cell carcinoma (1 paper, 2022). Esophageal squamous cell carcinoma (ESCC) is a type of esophageal carcinoma (EC) that can affect any part of the esophagus, but is usually located in the upper or middle third. "In the high incidence region of Hebei Province, the C/C genotype of XPC exon 15 appears to increase the risk of developing esophageal squamous cell carcinoma in the non-smoking population." (PMID 35069899, 2022).
Fuchs endothelial corneal dystrophy (1 paper, 2022). Fuchs endothelial corneal dystrophy (FECD) is the most frequent form of posterior corneal dystrophy (see this term) and is characterized by excrescences on a thickened Descemet membrane (corneal guttae), generalized corneal edema, with gradually decreased visual acuity. "Studies in humans looking at the NER expression profiles in Fuch’s endothelial corneal dystrophy (FECD) found that XPC was downregulated in patients that had FECD." (PMID 35205145, 2022).